TTLL4 (tubulin tyrosine ligase like 4)
Description:
Monoglutamylase which modifies both tubulin and non-tubulin proteins, adding a single glutamate on the gamma-carboxyl group of specific glutamate residues of target proteins. Involved in the side-chain initiation step of the polyglutamylation reaction but not in the elongation step. Preferentially modifies beta-tail tubulin over the alpha-tubulin. Monoglutamylates nucleosome assembly proteins NAP1L1 and NAP1L4. Monoglutamylates nucleotidyltransferase CGAS, leading to inhibition of CGAS catalytic activity, thereby preventing antiviral defense function. Involved in KLF4 glutamylation which impedes its ubiquitination, thereby leading to somatic cell reprogramming, pluripotency maintenance and embryogenesis.
Synonyms: KIAA0173
Tractability: PROTAC: ubiquitination databases record sites on it.
Gene: Protein-coding gene on chromosome 2 (218,710,809 to 218,755,416, forward strand). Ensembl gene ENSG00000135912.
Subcellular location: Cytoplasm; Cell projection, cilium; Cytoplasm, cytoskeleton, cilium basal body
Subcellular location (Human Protein Atlas): Mitochondria
Pathways (Reactome):
Metabolism of proteins: Carboxyterminal post-translational modifications of tubulin
Gene Ontology:
Molecular function: protein-glutamic acid ligase activity; protein-glutamic acid ligase activity, initiating; tubulin binding; tubulin-glutamic acid ligase activity
Biological process: microtubule cytoskeleton organization; peptidyl-glutamic acid modification; protein polyglutamylation
Cellular component: ciliary basal body; cytoplasm; cytosol; 9+0 non-motile cilium; cilium
Genetic constraint (gnomAD): Loss-of-function variants: 81 observed, 129.15 expected, observed/expected ratio (o/e) 0.63, 90% interval 0.52 to 0.75. The upper end of that interval is the gene's LOEUF score, 0.75, which puts it in group 3 of 6, group 1 being the genes least tolerant of losing a copy. Missense variants: 1,325 observed, 1,526.5 expected, observed/expected ratio (o/e) 0.87, 90% interval 0.83 to 0.91. Synonymous variants: 534 observed, 580.1 expected, observed/expected ratio (o/e) 0.92, 90% interval 0.86 to 0.99.
Homologues: Orthologues: macaque TTLL4 (96% identical), chimpanzee TTLL4 (94% identical), pig TTLL4 (84% identical), dog TTLL4 (84% identical), rat Ttll4 (81% identical), mouse Ttll4 (80% identical), guinea pig TTLL4 (77% identical), rabbit TTLL4 (73% identical), tropical clawed frog ttll4 (43% identical), zebrafish ttll4 (41% identical), Drosophila melanogaster TTLL4B (25% identical), Drosophila melanogaster TTLL4A (24% identical), and 1 more. Paralogues in human: TTLL6 (15% identical), TTLL13 (13% identical), TTLL2 (13% identical), TTLL7 (13% identical), TTLL11 (12% identical), TTLL1 (10% identical), TTLL9 (9% identical), TTLL3 (9% identical), TTLL10 (9% identical), TTLL8 (8% identical), TTLL12 (8% identical), KPRP (5% identical).
Diseases named in the same sentence as TTLL4 in open-access papers:
TTLL4 is named in the same sentence as 16 diseases in open-access papers, as found by Europe PMC text mining. Sharing a sentence is not in itself a finding about the gene and the disease. The quoted sentences say what the papers report.
breast carcinoma (9 papers, 2020 to 2025). "The cytoskeleton-associated protein Tubulin Tyrosine Ligase Like 4 (TTLL4) overexpression in breast cancer cells is associated with brain metastasis and alters small EVs biogenesis." (PMID 37091342, 2023). "A study screened for genes with correlation for brain metastasis by microarray and showed that TTLL4, a tubulin glutamylase enzyme, overexpression in breast cancer cells is associated with brain metastasis." (PMID 35295905, 2022). "A recent study showed that tubulin tyrosine ligase-like 4 (TTLL4) overexpression in breast cancer cells is associated with increased polyglutamylation of TubB, alteration of exosome homeostasis, and brain metastasis." (PMID 35008169, 2021). "In summary, here we demonstrate that TTLL4 was the only cytoskeleton-associated protein whose up-regulation in breast cancer cells correlated with the formation of brain metastasis." (PMID 32998758, 2020). "Analysis of proteins correlating with the abundance of breast cancer brain metastasis revealed that among these the only cytoskeletal-associated protein was TTLL4, a ligase that catalyzes the first addition of glutamate residue to proteins." (PMID 32998758, 2020). "Moreover, the upregulation of TTLL4 in breast cancer cells has been linked to the formation of brain metastases, modulating the interactions between breast cancer and vascular endothelial cells." (PMID 40599993, 2025). "Overexpression of tubulin tyrosine ligase like 4, which codes for a cytoskeleton-associated protein, accelerates the velocity of secretory vesicles and multivesicular bodies, thereby promoting brain metastasis of breast cancers." (PMID 38495881, 2024). "In breast cancer, TTLL4-mediated polyglutamylation of microtubules disrupts exosome homeostasis by regulating the transport of multivesicular bodies (MVBs), thereby promoting the formation of breast cancer brain metastases." (PMID 40599993, 2025). "Upregulation of TTLL4 in breast cancer cells promotes small EVs secretion, which increases the permeability of BBB endothelial cells and the adhesion of TNBC to endothelial cells, allowing tumor cells to pass through the BBB more easily." (PMID 37091342, 2023). "For the TNBC subtype, although understanding of the identified subtype-specific genes is less than other two types, the roles of DGCR5, RAD51L1, and TTLL4 in breast cancer are well studied." (PMID 35646077, 2022). "The correlation between TTLL4 expression and the overall survival of breast cancer patients showed the same trend and was nearly significant (p = 0.05)." (PMID 32998758, 2020). "In conclusion, these results show that up-regulation of TTLL4 in breast cancer cells promotes secretion of EV populations that increase permeability of endothelial cells of the BBB as well as tumour cell adhesion to these cells." (PMID 32998758, 2020). "Interestingly, the overexpression of the enzyme tubulin tyrosine ligase such as 4 (TTLL4) in breast cancer cells increases the secretion of exosomes and accelerates the movement of secretory vesicles and MVBs from TTLL4+ cells." (PMID 37958619, 2023). "Overexpression of TTLL4 (TTLL4plus) in MDA-MB231 and MDA-MB468 breast cancer cells (TTLL4plus cells) significantly increased polyglutamylation of β-tubulin." (PMID 32998758, 2020). "In comparison with luminal breast cancer patients, tumours from HER2+ and triple-negative BC patients showed significantly higher TTLL4 mRNA levels (p < 0.005)." (PMID 32998758, 2020). "We next analyzed whether TTLL4 overexpression may also alter adhesion of breast cancer cells independent of EVs." (PMID 32998758, 2020). "In addition, independent of EVs, TTLL4 overexpression increases adhesion of breast cancer cells." (PMID 32998758, 2020).
liver cancer (2 papers, 2024 to 2025). An epithelial or non-epithelial malignant neoplasm that arises from the liver. "Notably, TUBA1B and TTLL4 are the only two genes in this pathway that are highly expressed and associated with poor prognosis in the TCGA liver cancer dataset, with TTLL4 exhibiting a higher hazard ratio than TUBA1B." (PMID 40599993, 2025).
pancreatic cancer (2 papers, 2025). "Although its precise functions have not been extensively elucidated, TTLL4 has been implicated in the malignant progression of breast and pancreatic cancer." (PMID 40599993, 2025).
male infertility (1 paper, 2022). The inability of the male to effect fertilization of an ovum after a specified period of unprotected intercourse. "Given that depletion of Ttll1 or Ttll4 ameliorated neuronal degeneration in pcd mice, we assessed whether knocking out Ttll1 or Ttll4 could also rescue male infertility." (PMID 35404950, 2022). "However, only loss of Ttll1 but not Ttll4 corrected the excessive tubulin polyglutamylation in pcd cerebellum and loss of none of the Ttlls rescued male infertility." (PMID 35404950, 2022).
tumor (3 papers, 2020 to 2025). "TTLL4 is a key enzyme involved in the carboxy-terminal PTMs of tubulin, which are associated with tumor progression." (PMID 40599993, 2025). "Tubulin tyrosine ligase-like 4 (TTLL4) has been linked to tumor progression, but its specific role in HCC pathogenesis remains unclear." (PMID 40599993, 2025). "RNA was then extracted from these 19 paired samples for qRT-PCR analysis, which confirmed that TTLL4 expression was notably elevated in tumor tissues." (PMID 40599993, 2025). "In vivo, TTLL4 knockdown slowed tumor growth and reduced lung metastasis." (PMID 40599993, 2025). "In summary, our data show that high TTLL4 expression alters the EV populations and ingenuity pathway analysis indicates that EVs derived from TTLL4plus cells contain proteins involved in the regulation of malignant progression of tumour cells." (PMID 32998758, 2020). "In animal studies, TTLL4 knockdown effectively inhibited the origin and metastasis of HCC cells, resulting in significant reductions in tumor volume and metastatic burden." (PMID 40599993, 2025). "Correspondingly, a strong correlation of high TTLL4 levels and the lack of estrogen and progesterone receptor in tumour tissue was found (p < 0.001 and p = 0.001, respectively)." (PMID 32998758, 2020). "Interestingly, primary tumours that later developed brain and lung metastasis were characterized by higher TTLL4 levels compared with tumours without and these differences were statistically significant (p = 0.004 and p = 0.02, respectively)." (PMID 32998758, 2020).
bacterial infection (1 paper, 2017). "Consistently, Ttll4−/− and Ttll13−/− mice succumbed to bacterial infection." (PMID 28794449, 2017).
cancer (1 paper, 2025). A tumor composed of atypical neoplastic, often pleomorphic cells that invade other tissues. "TTLL4 was upregulated in HCC and associated with poor prognosis, linking it to cancer progression and the PI3K–AKT signaling pathway." (PMID 40599993, 2025).
infection (1 paper, 2017). The state of being infected such as from the introduction of a foreign agent such as serum, vaccine, antigenic substance or organism. "We observed that Ttll4−/− andTtll13−/− mice had higher bacterial loads in fecal, spleen, liver, and blood on day 8 post infection compared with their littermate WT control mice." (PMID 28794449, 2017). "Following infection with C. rodentium, Ttll4−/− and Ttll13−/− mice displayed much more persistent intestinal damage, encompassing greater epithelial injury, crypt hyperplasia, and more infiltration of inflammatory cells, than those of their littermate WT control mice." (PMID 28794449, 2017).
TTLL4 also shares sentences with these, for which no sentence is quoted: Autoimmunity (1 paper); cerebellar degeneration (1); COVID-19 (1); Hepatitis (1); hepatocellular carcinoma (1); pancreatic ductal adenocarcinoma (1); vascular tumor (1); viral infection (1).